PHF24 (PHD finger protein 24)
Synonyms: GINIP; formerly KIAA1045
Tractability: PROTAC: its protein half-life has been measured.
Gene: Protein-coding gene on chromosome 9 (34,957,608 to 34,982,544, forward strand). Ensembl gene ENSG00000122733.
Gene Ontology:
Molecular function: protein binding; transcription corepressor activity
Biological process: negative regulation of DNA-templated transcription
Cellular component: cytoplasm; nucleus; glutamatergic synapse; synaptic vesicle membrane
Genetic constraint (gnomAD): Loss-of-function variants: 25 observed, 43.48 expected, observed/expected ratio (o/e) 0.57, 90% interval 0.42 to 0.8. The upper end of that interval is the gene's LOEUF score, 0.8, which puts it in group 3 of 6, group 1 being the genes least tolerant of losing a copy. Missense variants: 470 observed, 556.83 expected, observed/expected ratio (o/e) 0.84, 90% interval 0.78 to 0.91. Synonymous variants: 185 observed, 213.94 expected, observed/expected ratio (o/e) 0.86, 90% interval 0.77 to 0.98.
Homologues: Orthologues: chimpanzee PHF24 (99% identical), macaque PHF24 (98% identical), pig PHF24 (93% identical), rabbit PHF24 (92% identical), mouse Phf24 (91% identical), rat Phf24 (91% identical), guinea pig PHF24 (88% identical), tropical clawed frog phf24 (65% identical), zebrafish phf24 (53% identical), Drosophila melanogaster TpnC41C (3% identical), Drosophila melanogaster TpnC73F (3% identical), Drosophila melanogaster TpnC47D (2% identical). Paralogues in human: EFCAB6 (14% identical), CAPS2 (12% identical), SPATA21 (8% identical), CAPS (8% identical), CAPSL (6% identical).
Diseases named in the same sentence as PHF24 in open-access papers:
PHF24 is named in the same sentence as 6 diseases in open-access papers, as found by Europe PMC text mining. Sharing a sentence is not in itself a finding about the gene and the disease. The quoted sentences say what the papers report.
cognitive deficits (2 papers, 2022 to 2025). "Moreover, increased seizure sensitivity, emotional defects, and cognitive impairment were reported in PHF24-null rats." (PMID 35866480, 2022).
astrocytoma (1 paper, 2024). "KIAA1045 (PHD finger protein 24) and SYT13 (Synaptotagmin 13) genes have been recognized as hubs in 2021 astrocytoma, but the average of their 2016 percentage measures is 4 and 8, respectively." (PMID 39286768, 2024).
autoimmune disease (1 paper, 2024). A disorder resulting from loss of function or tissue destruction of an organ or multiple organs, arising from humoral or cellular immune responses of the individual to their own tissue constituents. "Others were associated with autoimmune disease, such as systemic lupus erythematosus (SLE), ALS, and RA: CHIT1, IL18RAP, PHF24, and TPST1." (PMID 38978787, 2024).
PHF24 also shares sentences with these, for which no sentence is quoted: Anxiety (1 paper); Stroke (1); systemic lupus erythematosus (1).